MYC (MYC proto-oncogene, bHLH transcription factor)
Diseases named in the same sentence as MYC in open-access papers (continued):
Sharing a sentence is not in itself a finding about the gene and the disease.
tumor (continued). "In the present study, we asked whether the presence of Sirt2 slows or enhances tumor growth in a c-MYC-driven mouse model of HCC." (PMID 37628798, 2023). "These strategies offer potential avenues to inhibit MYC’s function and suppress tumor growth." (PMID 37755397, 2023). "Intriguingly, IGF2BP3 could stabilize MYC and increase its expression, establishing a positive feedback mechanism to expedite tumor deterioration." (PMID 37554271, 2023). "Further evidence for this series of oncogenic events came from the fortuitous capture of tumour-associated TAL2/3 cells that displayed a pre-transformed state retaining TFCP2L1 activity, while at the same time showing MYC and YY1 activity accompanied by a hypoxia and stress signature." (PMID 37236926, 2023). "Therefore, MYC can promote tumor progression directly as well as give rise to tumor immunosuppression, which can indirectly result in tumor progression by regulating CD47 and PD-L1." (PMID 37221625, 2023). "Moreover, MYC, one of the elevated oncogenic signaling in immunotherapy-resistant ‘cold’ tumors, has been reported to regulate the tumor microenvironment through effects on both innate and adaptive immune effector cells and immune regulatory cytokines." (PMID 37190266, 2023). "It remains to be fully determined, however, how this loss of circadian control of metabolism and gain of heightened metabolic flux in MYC-amplified tumor cells may directly contribute to tumorigenesis." (PMID 37639465, 2023). "The oncogene MYC is dysregulated in a host of human cancers, and as an important point of convergence in multitudinous oncogenic signaling pathways, it plays a crucial role in tumor immune regulation in the tumor immune microenvironment (TIME)." (PMID 36966168, 2023). "Azacitidine treatment of a primary UL culture decreases tumour cell viability (probably via hypomethylation/activation of tumour-suppressor genes), ECM production and the expression of genes encoding WISP1, c-MYC and MMP7 proteins, which are the targets of the WNT/β-catenin signalling pathway." (PMID 36982825, 2023). "These included an HRAS cassette exon repressed by MYC across multiple tumor types." (PMID 37399401, 2023). "Numerous studies have shown that the MYC-dependent pathway in tumor cells can indirectly affect the expression of cytokines in the TIME, such as the reduction in the expression of interleukin-2 (IL-2), interferon-γ (IFN-γ), and perforin and the increase in the expression of interleukin-6 (IL-6)." (PMID 36966168, 2023). "However, MYC activation has been noted to broadly suppress miRNA expression, some with tumor suppressor effects, such as miR-34a, miR-15a, and miR-16-1, which is advantageous for tumor development." (PMID 39534571, 2023). "As MYC protein expression is slightly downregulated after treatment with IFN-γ, IFNs may increase MHC-I expression in tumor cells that demonstrate high MYC expression." (PMID 37660039, 2023). "Omomyc, one of the most effective MYC inhibitors, strongly promotes tumor regression." (PMID 37400551, 2023). "In addition, MYC plays an important role in regulating glutamine transportation and catabolism in tumor cells." (PMID 36994237, 2023). "The reason could be that, within each tumour grade group, higher expression of MYC correlates with better prognosis." (PMID 37400829, 2023). "Inhibition of MYC leads to cell cycle arrest and apoptosis in several types of tumor cells." (PMID 37173935, 2023). "FACS-sorted T-ALL tumor cells were treated with the MYC inhibitor 10058-F4." (PMID 36897988, 2023). "Notably, both MYC expression and m6A levels of nude mice tumor tissues were reduced in the SHMT2 knockdown group." (PMID 37932821, 2023).
tumor (continued). "Interestingly, the expression levels of MYC-target genes were significantly reduced after genetic and pharmaceutical ablation of PRMT1, which was consistent with previous reports depicting MYC as a suppressor of anti-tumor immunity." (PMID 37193698, 2023). "The c-MYC level was estimated immunohistochemically in tumor sections." (PMID 36768815, 2023). "Our in vitro findings prompted us to address whether MYC was also a tumor cell–intrinsic driver of mTORi resistance in vivo." (PMID 37642941, 2023). "Second, due to the lack of detailed information on the patients, this study did not analyze the associations between BAX, BCL2 and c-MYC polymorphisms and gene expression and clinical features, such as tumor size and sensitivity to treatment." (PMID 38003498, 2023). "In summary, these findings suggest that the upregulation of Cdkn2a in GTML as compared to GMYC might reflect a clinically relevant feature also present and affecting tumor prognosis between MYC-high and MYCN-high human Group 3/4 MBs." (PMID 36869047, 2023). "In addition, various studies have shown that STAT3/MYC signaling can regulate tumor energy metabolism and the microenvironment to impact tumor cell proliferation and metastasis." (PMID 36873736, 2023). "As a result, c-MYC is considered an important oncogene effective in tumor progression." (PMID 36843070, 2023). "Further study is required to assess whether increased mtDNAcn (or de novo mtDNA synthesis) is required for tumor development and progression in MYC-driven cancers." (PMID 37971875, 2023). "The IMP1, c-MYC, and Survivin increased significantly in the intranuclear tumor cell locations." (PMID 37336938, 2023). "GSVA results showed that MYC was enriched in the luminal subset 1, indicating that these luminal cells may have characteristics of strong tumor growth, metastasis, immune evasion, and metabolic ability." (PMID 37221625, 2023). "For instance, compounds L20, N1, N3, N6, and N7 may be targeting alternative pathways beyond MYC, inhibiting tumor cell proliferation." (PMID 38275631, 2023). "Thus, we propose that B220+Ig-GL7+CD43- spleen cells represent a Pro-B/Pre-B population that is able to escape the BM and populate the secondary lymphoid organs of pre-tumor stage λ-MYC mice." (PMID 37809061, 2023). "HDAC3 initiates tumor activity by regulating the FOXA2-mediated FTO/m6A/MYC axis." (PMID 37932821, 2023). "Previous studies have shown that pevonedistat may upregulate PD-L1 expression by the tumor cells via MYC oncogene." (PMID 37031300, 2023). "In addition, specific and efficient delivery technologies to deliver MYC-inhibiting agents into MYC-dependent tumor cells are just beginning to emerge." (PMID 36969025, 2023). "Furthermore, detailed time-course studies revealed that the combination therapy considerably delayed the progression of c-MYC/Mcl1 tumor lesions." (PMID 37040183, 2023). "Therefore, in the following sections, we will review the rewired tumor metabolism in relation to MYC deregulation." (PMID 37443779, 2023). "In C1 subtype, cell cycle-related pathways such as E2F targets, G2M checkpoint, MYC targets, and DNA repair were strikingly enriched, while immune response-related pathways were relatively inhibited, which was consistent with high tumor proliferation rate of C1." (PMID 36726580, 2023). "Furthermore, we explore the impact of MYC on the tumor microenvironment, including immune evasion, angiogenesis and cancer-associated fibroblast remodeling." (PMID 37755397, 2023).
tumor (continued). "Through GSVA and GSEA, we observed a significant activation of tumor-associated biological processes such as EMT, cell proliferation (MYC targets, E2F targets, G2M checkpoints, and cell cycle), and signaling pathways like WNT/β-catenin and PI3K/AKT/MTOR pathways in the high PCDI score group." (PMID 38170006, 2023). "Likewise, MYC effectively activates the expression of IGF2BP3 by binding to its promoter to drive tumor progression and metastasis." (PMID 37554271, 2023). "It has been reported that MYC targets and Hedgehog signaling are more active in tumor tissues." (PMID 37035151, 2023). "Conversely, tumor cells that showed high nuclear MYC expression stained poorly for RUNX3." (PMID 37400551, 2023). "The c-MYC/PI3K/AKT/mTOR axis can be targeted to decrease tumor progression." (PMID 37895357, 2023). "In the case of enzymes involved in serine biosynthesis or transport proteins, such as SLC7A5, SLC1A5 and SLC43A1, the upregulation of MYC in a positive feedback manner could rewire the whole tumor metabolism." (PMID 37443779, 2023). "These mice were resistant to tumor formation suggesting that tumors demand elevated MYC levels." (PMID 37941901, 2023). "High c-MYC signal was observed in BrC4f_Hyp2 tumor sections." (PMID 36768815, 2023). "HNRNPH Gene Expression Decreases with MYC Activation across Multiple Tumor Types." (PMID 37399401, 2023). "In addition, the tumor volumes decreased after discontinuation of DOX administration, indicating the dependence of the tumor growth on the expression of MYC and PIK3CAE545K." (PMID 36763589, 2023). "N5-methylglutamine was detectable in the urine of wt/wt mice, and its creatinine-normalized levels were increased in all mice with β-catenin/c-MYC-driven tumors, demonstrating a significant positive correlation with tumor burden (Pearson r = 0.8 and P = 0.016)." (PMID 36280791, 2023). "Therefore, the development of a drug with high selectivity for c-MYC G4 structure and robust anti-tumor activity holds promise as a reliable choice for TNBC therapy, bearing crucial significance in improving the prognosis of TNBC patients." (PMID 38275631, 2023). "Additional genes where CN levels are known to vary in HGSOC were assessed to determine whether this intra-tumor heterogeneity in CN occurs for other genes in our cohort, for example, MYC is frequently amplified in HGSOC cases." (PMID 37220750, 2023). "Furthermore, the AFP vaccine effectively prevented c-MYC/Mcl1 HCC initiation when administered before tumor formation, while it was ineffective against full-blown c-MYC/Mcl1 tumors." (PMID 37040183, 2023). "Despite all difficulties in effectively inhibiting MYC in tumor cells, genetic models indicate that MYC inhibition could be supportable for an organism and lead to sustainable tumor regression." (PMID 36969025, 2023). "CDK12 was previously reported to regulate MYC expression in other tumour context." (PMID 37599362, 2023).
tumor (continued). "Based on Molecular Signatures Database (MSigDB) hallmark pathway annotation, the prognostic modules were most enriched for pathways essential for tumor development, including E2F targets, G2M checkpoints, epithelial–mesenchymal transitions (EMTs), MYC targets, and inflammatory responses." (PMID 37907329, 2023). "Modifying G4 motifs in the MYC promoter drives oncogenesis by reducing the expression of MYC and thereby disrupting cell proliferation, migration, immune evasion, and metabolism, resulting in reduced tumor progression." (PMID 37323535, 2023). "Thus, studies on the regulatory effect of METTL3 on MYC expression, mediated either directly or indirectly by m6A, in the context of tumor growth are expected to provide a new therapeutic strategy for tumors." (PMID 37996892, 2023). "Interestingly, FBXO28 is found to exert either oncogenic or tumor suppressing functions by targeting MYC, SMARCC2 or HIF-1α, under different cellular contexts, complicating its role in tumorigenesis and metastasis." (PMID 37596321, 2023). "Although SMARCA4 loss or MYC overexpression did not increase proliferation of GCPs in vitro, the combination of both alterations induced tumor formation after orthotopic transplantation in vivo." (PMID 37919824, 2023). "We examined the expression of c-MYC in 40 ESCC tumor samples and normal tissues that matched." (PMID 36624401, 2023). "Notably, in contrast to RhOME2, RhOME1 (PCAT1) and RhOME3 (CCDC26) were previously identified as MYC regulatory regions in other tumor entities." (PMID 38040699, 2023). "Additionally, Myc phosphorylated on T58 reduces the expression of BIM, which is particularly relevant as a tumour suppressor in MYC-driven B cell leukaemia." (PMID 36902175, 2023). "Notably, even transient inactivation of MYC leads to tumor regression, suggesting that the modulation of oncogenic MYC is a feasible strategy for cancer treatment." (PMID 37496997, 2023). "Such enhancers can be targeted by bromodomain and extra-terminal (BET) inhibitors (BETi) or degraders and this review discusses whether integrated SOS1 inhibition and BET targeting of MYC synergizes against mutant KRAS tumor growth." (PMID 38023987, 2023). "In addition to promoting the expression of oncogenes, MYC inhibits the expression of some tumor suppressor genes, such as p15INK4B and p21Cip1, by combining with Miz-1 to promote tumor growth." (PMID 36717782, 2023). "In light of our results, we reasoned that c-MYC could be the functionally relevant target that mediates the tumor-suppressive effects of miR-616." (PMID 37685841, 2023). "BET inhibitors preclinically impaired tumor growth in MYC-dependent cancers, including SCLC." (PMID 37422534, 2023). "MYC promotes cholesterol biosynthesis in tumor cells and supports cell proliferation through SQLE." (PMID 37064135, 2023). "Furthermore, MYC-driven tryptophan catabolism activates the production of kynurenine, promoting the nuclear translocation of AhR to promote tumor growth." (PMID 36755301, 2023). "Nonetheless, whether synergistic effects between EBV and MYC/BCL2/BCL6 aberrations contribute to the pathogenesis of this subset of tumours remains to be established." (PMID 36836878, 2023). "Metabolomic characterization of the three WM tumor types confirmed previous observations seen when acutely switching on MYC in tumors, including an increase in the levels of several amino acids, as well as phosphatidylethanolamine (PE)/phosphatidylcholine (PC) and phosphatidylglycerol (PG) 17,19." (PMID 37946084, 2023). "In tumours treated with enzalutamide alone or with a combination of enzalutamide and CT7001, GSEA identified negative enrichment of several gene sets, including the hallmark androgen response, MYC targets, reactive oxygen species and fatty acid metabolism." (PMID 37076563, 2023). "In human cancers, dysregulated expression of MYC greatly promotes tumor cell proliferation." (PMID 37996892, 2023).
tumor (continued). "Proliferation relative pathways tumor proliferation (spearman = 0.71, p < 0.01), G2M checkpoint (spearman = 0.78, p < 0.01), DNA replication (spearman = 0.55, p < 0.01), MYC targets (spearman = 0.39, p < 0.01) showed a robust correlation." (PMID 37789080, 2023). "Finally, a new differential expression analysis with the exclusion of the samples (both adjacent mucosa and tumor tissues) of patients with a MYC amplification was carried out." (PMID 36366788, 2023). "Understanding MYC’s multifaceted role in driving drug resistance and tumor progression is crucial for developing targeted therapies and combination treatments that may effectively combat this devastating disease." (PMID 37755397, 2023). "In addition, the experimental liver and lung metastasis models were also generated to evaluate the effects of REG1α and MYC on tumor cell metastasis." (PMID 37626036, 2023). "In addition, it is also suggested that the suppression of MYC and mTORC1 signature contributed to the tumor growth inhibition." (PMID 36897912, 2023). "Notably, TIGIT inhibition induces a reduction in tumor burden, prolonged survival in preclinical Vk*MYC MM models and prevents immune escape in myeloma murine models undergoing stem cell transplant." (PMID 38213954, 2023). "In contrast, HNRNPF exhibited a positive correlation with MYC activation in almost all tumor types." (PMID 37399401, 2023). "Therefore, combining therapy targeting the MYC pathway with intervention in glutamine metabolism should be key to reversing MYC-driven tumor growth and restoring the antitumor immune response." (PMID 36959802, 2023). "Degradation of MYC led to tumor regression in multiple xenograft mouse models." (PMID 37233863, 2023). "MYC could enhance cholesterol biosynthesis and dysregulate cholesterol transport and storage, leading to tumor cell progression." (PMID 37938654, 2023). "MYC in tumor cells influences Treg accumulation, activation and metabolic programming." (PMID 37755397, 2023). "Considering this information, we propose the hypothesis that the downregulation of circFAM13B in MB may upregulate IGF2BP1 expression levels and, thus, promote tumor growth through deregulation of the MYC and FSCN1 oncogenes." (PMID 37835380, 2023). "In addition, the expression profile of Ctdnep1-cKO-tumor cells exhibited a greater similarity to that of MYC-driven G3 MB mouse models when compared with Ctdnep1-cKO NPCs and control NPCs." (PMID 36765089, 2023). "We established a new MYC-driven T-ALL tumor-derived cell line from this background." (PMID 36897988, 2023). "Its gene product, the MYC transcription factor, regulates the transcription of thousands of genes, controlling multiple biological processes, including cell growth and differentiation, as well as tumor-initiating and advancing the tumor." (PMID 37342196, 2023). "Furthermore, miR-1827 was shown to prevent tumor development by lowering MYC and FAM83F levels in in vivo tests." (PMID 37986065, 2023). "Furthermore, high expressed c-MYC stimulates aerobic glycolysis, reinforcing the adaptation of tumor cells to oxidative stress." (PMID 36721232, 2023).